EIF4A2 (eukaryotic translation initiation factor 4A2)
Diseases named in the same sentence as EIF4A2 in open-access papers (continued):
Sharing a sentence is not in itself a finding about the gene and the disease.
cancer (24 papers, 2011 to 2025). A tumor composed of atypical neoplastic, often pleomorphic cells that invade other tissues. "EIF4A2 mutations are found in 0.7% of ccRCC, when found in other types of cancer, these mutations are associated with unfavorable prognosis and resistance to therapy." (PMID 37940875, 2023). "eIF4A1 levels are increased in several cancers and predict poor prognosis, whilst high eIF4A2 levels are linked to better survival rates." (PMID 31180491, 2019). "To elucidate the molecular mechanism underlying BLF1’s selective cytotoxicity toward cancer cells while sparing normal cells at low concentrations, we characterized its effects on the ATPase activities of the eIF4A1 and eIF4A2 proteins using an in-vitro reconstitution system." (PMID 40423315, 2025). "Although few cellular functions of EIF4A2 have been discovered, positive associations between EIF4A2 and various cancers, including CRC, have been investigated, suggesting that EIF4A2 may be a novel mediator of CRC recurrence." (PMID 31578316, 2019). "In conclusion, this study provides a fundamental resource for the cancer research community by finding highly specific antibodies to study eIF4A1 and eIF4A2 at the protein level." (PMID 41299109, 2025). "The development of paralog-specific antibodies for eIF4A1 and eIF4A2 represents a significant advancement in studying their distinct roles in translational control of many hallmarks in cancer biology." (PMID 41299109, 2025). "To address these, we developed paralog-specific, affinity-purified rabbit peptide antibodies to investigate the distinct contributions of eIF4A1 and eIF4A2 in cancer biology." (PMID 41299109, 2025). "In cell-free systems, EIF4A2 can perform the same functions as EIF4A1, but rarely compensates for the loss of EIF4A1 in cancer cell lines." (PMID 38011999, 2024). "Although little is known about eIF4A2 in cancer, recent studies have revealed the upregulation of this isoform in colorectal cancer and paclitaxel-resistant breast cancer." (PMID 36768380, 2023). "While eif4a2 gene is considered a novel target for cancer therapy and anti-cancer drug discovery, its inhibition prevents the cooperation between eif4a2 and oncogenes, and thus effectively inhibits the replication of cancer and tumor." (PMID 36506559, 2022). "Dendritic cells, CD8+ T cells, and neutrophils had higher infiltration levels in cancers with higher eIF4A2 mRNA expression." (PMID 34869305, 2021). "Next, we used siRNA approach to selectively knock-down their expression and observed that EIF4A2 expression decreased when knocking-down ZNF143 both in cancer cells." (PMID 31088567, 2019). "Additionally, further research on the roles of eIF4A1 and eIF4A2 in cancer development is warranted." (PMID 40423315, 2025). "Importantly, some of the notable DAPs were recognized as hypoxia-responsive in human cancers, of which EIF4A2 is the most documented." (PMID 34440794, 2021). "EIF4A2, a eukaryotic translational initiation factor takes part in protein synthesis that might be related to an altered translational landscape of cancer cells." (PMID 33639650, 2021). "We identified genes for which ASEs were observed in both the Afro-Caribbean cohort and the Jurkat cells expressing Tax or HBZ, including cancer genes EIF4A2, IKBKB, LZTR1, STAT6 (for Tax); CARS, MDM2, IKZF1 (for HBZ); and EWSR1, MUTYH, and PTPRC (for both Tax and HBZ)." (PMID 34543356, 2021). "eIF4A2 is a paralogue of eIF4A1 and although the amino acid sequences of both proteins are highly similar they have opposing functions, resulting in contrasting effects of the helicases in cancer." (PMID 31180491, 2019). "In this study, we showed that full-length eIF4A1 and eIF4A2, sharing exactly 95.3% similarity in amino acid sequences, exhibit different enzymatic properties, which may result in their distinct roles in cancer development." (PMID 40423315, 2025).
cancer (continued). "Additionally, the ability to differentiate between eIF4A1 and eIF4A2 in tumor versus normal tissues may yield novel insights into their distinct roles in cancer biology." (PMID 41299109, 2025). "This could explain why EIF4A2 cannot fully compensate for loss of EIF4A1, especially in highly proliferative cell types with high metabolic demands such as GC B cells, which share these features with cancer cells." (PMID 38011999, 2024). "Additionally, the differences between eIF4A1 and eIF4A2, which have been underestimated by previous studies, potentially provide an opportunity for developing selective therapeutic interventions that specifically target cancer cells while leaving normal cells intact." (PMID 40423315, 2025). "Among these, we found an overlap in the amplification frequencies of three different snoRNA/host gene couples, namely SNORA63/EIF4A2, SNORA63E/LINC00888, SNORD66/EIF4G1, in five different cancer types: HNSC, KIRC, SKCM, OV, and GBM." (PMID 32046192, 2020). "Two candidate target genes (EIF4A2 and ANKRD46) were selected for analysis of correlation with clinicopathological characteristics and prognosis using immunohistochemistry on cancer tissue microrrays." (PMID 21219636, 2011). "Mechanically, EIF4A2 as a transcriptional target of ZNF143 might function via mediating the translation of c-Myc, an oncoprotein that is deregulated in more than 50% human cancers and is related to cancer cell aggressive phenotypes, and drug resistance." (PMID 38023215, 2023). "Interestingly, eIF4A1, but not eIF4A2, is a common essential gene in most cancer cell lines in CRISPR knockout screens." (PMID 37874652, 2023). "Moreover, Large-Scale, Deep RNAi Screening in Project DRIVE across 398 cancer cell lines also indicates that EIF4A2 is not essential for cell proliferation." (PMID 31088567, 2019).
tumor (19 papers, 2014 to 2026). "Conversely, eIF4A2 has been implicated in translational repression and microRNA-mediated gene silencing, indicating a potential tumor-suppressive role in specific contexts." (PMID 41299109, 2025). "We hypothesized that the varying effects of BLF1 in tumor and healthy cells may be caused by its differential effects on eIF4A1 and eIF4A2." (PMID 40423315, 2025). "All these results suggest that abnormal EIF4A2 expression may be associated with tumor metastasis and oxaliplatin resistance in CRC." (PMID 31088567, 2019). "Consistently, reduction of mRNA translation with rapamycin in Eif4a2-deleted tumours suppresses senescence and restores tumorigenesis." (PMID 42163342, 2026). "Six upregulated and mutated tumor antigens related to NMD, and infiltration of APCs were identified in patients with BLCA, including HP1BP3, OSBPL9, SSH3, ZCCHC8, FANCI, and EIF4A2." (PMID 36761744, 2023). "It has been shown that miR-5195-3p is downregulated in PTX-resistant tumor tissues and cell lines, while the upregulation of miR-5195-3p can increase drug sensitivity via targeting eukaryotic translation initiation factor 4A2 (EIF4A2)." (PMID 32122355, 2020). "Knocking-down EIF4A2 combined with oxaliplatin inhibited tumor volume and tumor weight significantly than that of shCTRL combined with oxaliplatin." (PMID 31088567, 2019). "This highlights the value of the development of small molecule inhibitors that specifically target eIF4A2 to target the therapy resistant hypoxic tumour microenvironment." (PMID 30405205, 2018). "Importantly, some Eif4a2 knockout cells overcome senescence to form tumours that exhibit enhanced MAP-kinase signalling and, in contrast to eIF4A2+/+ lesions, these were eradicated by administration of a MEK inhibitor." (PMID 42163342, 2026). "We found that the expression of EIF4A1, but not EIF4A2, was higher in tumor tissue and associated with poor clinical outcomes in LUAD patients." (PMID 36101357, 2022). "Contrary to these findings, eIF4A2 expression has been found to be low in tumor tissues but significantly related to three different clinicopathological features, namely, pathologic type, tumor grade, and overall survival." (PMID 34869305, 2021). "Oncogenes EIF4A2 and TNFRSF6B, which are overexpressed in tumours and described to inhibit apoptosis while promoting invasion and migration, were significantly downregulated alongside HuR and are suggestive of a pleiotropic effect." (PMID 37925433, 2023). "In contrast, similarly to what has been described in other tumor types, the treatment of HCC cells with these drugs led to eIF4A2 upregulation, which is considered a compensatory response to marked eIF4A1 suppression." (PMID 36768380, 2023). "Six tumor antigens (HP1BP3, OSBPL9, SSH3, ZCCHC8, FANCI and EIF4A2) were correlated with the expression of NMD factors and infiltration of APCs, which may be promising candidates for mRNA vaccines." (PMID 36761744, 2023). "In contrast, the protein levels of EIF4A2 (right two panels) did not change as tumor grades or stages changed." (PMID 36101357, 2022). "Heat shock-activated HSF1 is mainly responsive to the expression of heat shock proteins, while activation of HSF1 in tumor tissues is predominantly responsible for controlling the expression of non-heat shock proteins, e.g. CKS2, LY6K, RBM23, CCT6A, CKS1B, ST13 and EIF4A2." (PMID 25199534, 2014). "Similarly, higher protein levels of EIF4A1 but not EIF4A2 were detected in the tumor tissues of LUAD." (PMID 36101357, 2022).
tumor (continued). "The expression level of EIF4A1 in tumor tissues was higher than that in normal tissue samples of LUAD, but this was not the case for the expression of EIF4A2, and the expression levels were higher in the advanced stages and advanced lymph node status for EIF4A1 but not EIF4A2 (right two panels)." (PMID 36101357, 2022).
infection (6 papers, 2007 to 2025). The state of being infected such as from the introduction of a foreign agent such as serum, vaccine, antigenic substance or organism. "Eukaryotic initiation factor 4A-2 (EIF4A2), a host protein essential for cap-dependent translation, was consistently upregulated upon infection across all cell lines except for Vero cells." (PMID 41157297, 2025). "Intriguingly, the EIF4A2 isoform expressed during infection includes an additional, unannotated exon with a premature termination codon (PTC)." (PMID 39869630, 2025). "Lentiviral infection of shRNA targeting EIF4A2 in DLD1 and HCT116 cells significantly inhibited cell migration and invasion." (PMID 31088567, 2019).
neurodevelopmental disorder (2 papers, 2024). A behavioral and cognitive disorder with onset during the developmental period that involves impaired or aberrant development of intellectual, motor, or social functions. "In more detail, missense and loss-of-function variants in EIF4A2 (DDX2B) are associated with the Neurodevelopmental disorder with hypotonia and speech delay, with or without seizures (NEDHSS, #620455)." (PMID 39149612, 2024).
hematological cancer (1 paper, 2023). "This may be simply attributed to the expression levels of RocA targets (eIF4A1, eIF4A2 and DDX3X), which are much higher in hematological cancer tissues than in normal tissues (data not shown)." (PMID 36725859, 2023).
EIF4A2 also shares sentences with these, for which no sentence is quoted: liver cancer (2 papers); adult-onset Still disease (1); Alzheimer disease (1); autism (1); bipolar disorder (1); cervical cancer (1); COVID-19 (1); developmental delay (1); endometrial cancer (1); esophageal cancer (1); glioma (1); gynecological cancers (1); head and neck cancer (1); Hypertension (1); keratosis (1); lung adenocarcinoma (1); lymphoma (1); malignant glioma (1); malignant peripheral nerve sheath tumor (1); mental disorder (1); metabolic disorder (1); personality disorder (1); prostate carcinoma (1); pulmonary disorder (1); rectal cancer (1); retinitis pigmentosa (1); rheumatoid arthritis (1); Spinocerebellar Ataxia (1); squamous cell carcinoma (1); viral infection (1).